SESN2 (sestrin 2)
Diseases named in the same sentence as SESN2 in open-access papers (continued):
Sharing a sentence is not in itself a finding about the gene and the disease.
endometrial tumor (2 papers, 2019 to 2025). "Our results showed the lowest expression of SESN2 protein in KLE cells derived from a poorly differentiated G3 endometrial tumor isolated from colon metastasis." (PMID 31073887, 2019). "For example, a study of primary endometrial tumours showed that SESN2 expression was correlated with lower patient survival, and mTORC1 activity levels were higher in these tumours in the presence of Sestrins, suggesting dysfunctional Sestrin–mTORC1 signalling." (PMID 40361504, 2025). "Although SESN2 functions as expected in endometrial cell lines, SESN–mTORC1 signalling may be disrupted in the tumour microenvironment, as SESN2 levels do not correlate with reduced mTORC1 activity in endometrial tumours." (PMID 40361504, 2025).
Hepatic fibrosis (2 papers, 2022 to 2023). The presence of excessive fibrous connective tissue in the liver. "During hepatic fibrosis, SESN2 represses HSCs activation and intrahepatic inflammation, hindering the occurrence and progress of fibrogenesis." (PMID 36841824, 2023). "In summary, current studies have preliminarily revealed the implication of SESN2 in ameliorating hepatic fibrosis." (PMID 36841824, 2023). "HSCs-specific delivery of SESN2 reduces α-SMA-labeled activated HSCs and collagen deposition, thereby ameliorating prolonged CCl4- or BDL-induced hepatic fibrosis in mice." (PMID 36841824, 2023). "However, fibrogenesis involves multiple types of hepatic cells including HSCs, hepatocytes, Kupffer cells, liver sinusoidal endothelial cell, etc., thus, whether and how SESN2 in other types of hepatic cells influences the process of hepatic fibrosis remain inconclusive." (PMID 36841824, 2023). "Liver fibrosis was measured by Sirius red staining and was significantly increased by BDL to a greater extent in Sesn2−/− mice than in Sesn2+/+ mice." (PMID 35260799, 2022).
kidney damage (2 papers, 2022 to 2025). "Our study demonstrates that SESN2 is not only a viable therapeutic target for renal IRI but also responds to the extent of kidney damage, similarly to the kidney injury molecule KIM-1." (PMID 40485171, 2025). "A marked reduction of SESN2 expression was observed in the presence of nephropathy with the lowest levels observed in the presence of macro-albuminuria." (PMID 36476132, 2022). "Rubicon and mammalian target of rapamycin, the negative regulators of autophagy, are overexpressed in diabetic patients with nephropathy while, Sestrin-2 is down-expressed." (PMID 36476132, 2022). "In contrast to RUBCN, even in the absence of nephropathy, diabetic patients from G1 showed lower levels of SESN2 compared to healthy controls (6.47 ± 0.86 ng/mL and 8.04 ± 0.76 ng/mL respectively)." (PMID 36476132, 2022).
muscle atrophy (2 papers, 2022 to 2025). The loss of muscle tissue due to inactivity or disease. "Additionally, SESN2 mediated the protective effects of exercise against dexamethasone‐ and immobilization‐induced muscle atrophy, suggesting that SESN2 could be a promising therapeutic target for muscle atrophy." (PMID 41030226, 2025).
polycystic ovary syndrome (2 papers, 2023 to 2025). A disorder that manifests as multiple cysts on the ovaries. "This study aims to assess serum SESN2 levels in treatment-naive subjects with polycystic ovary syndrome (PCOS) and compare them to healthy controls." (PMID 40225432, 2025).
thyroid cancer (2 papers, 2021 to 2025). "At the same time, it is thought that detailed examination of the effect of SESN2 levels on the development of thyroid cancer may be useful both in terms of disease prognosis and the development of new treatment strategies." (PMID 40956676, 2025). "IMCA inhibited proliferation and induced apoptosis by promoting the translocation of the orphan nuclear receptor 4A1 from the nucleus to the cytoplasm, further increasing sestrin 2 expression and phosphorylated-AMPK levels, and decreasing p70S6K in the TT thyroid cancer cell line." (PMID 34784907, 2021).
ulcerative colitis (2 papers, 2016 to 2021). An inflammatory bowel disease involving the mucosal surface of the large intestine and rectum. "This study also has clinical relevance because sestrin 2 protein expression, which is elevated in patients with ulcerative colitis, was reduced by RE administration." (PMID 33673488, 2021). "This hypothesis is supported by earlier studies that have reported that sestrin 2 protein expression is increased in patients with ulcerative colitis." (PMID 33673488, 2021).
Abdominal obesity (1 paper, 2025). Excessive fat around the stomach and abdomen. "Conversely, in the diabetic cohort, higher SESN2 concentrations (T3) were associated with significantly higher odds of high triglycerides, high TyG x BMI, high TyG x waist circumference, high VAI, high LAP, high body fat, abdominal obesity, and high waist-to-hip ratio." (PMID 40433409, 2025).
acute pancreatitis (1 paper, 2026). An acute inflammatory process that leads to necrosis of the pancreatic parenchyma. "Notably, Sesn2, Kras, Hmox1, and Nfe2l2 exhibited significant expression differences during acute pancreatitis, suggesting they may serve as potential biomarkers for the condition." (PMID 41894401, 2026).
aortic stenosis (1 paper, 2025). Aortic valve stenosis is a aortic valve disease caused by the incomplete opening of the aortic valve. "While elevated plasma sestrin-2 levels have been observed in other cardiovascular conditions, increased sestrin-2 protein expression has been observed in aortic stenosis valves ex vivo." (PMID 40076529, 2025). "Sestrin-2 primarily plays a protective role in aortic stenosis by regulating reactive oxygen species production and preventing the oxidation of LDL." (PMID 40076529, 2025). "Among the sestrin family, sestrin-2 has been extensively studied in aortic stenosis due to its prominent role in oxidative stress responses." (PMID 40076529, 2025).
Arthritis (1 paper, 2024). Inflammation of a joint. "Our findings not only furnish a theoretical basis for further investigations but also kindle substantial interest in exploring the functions of SESN2 and its interplay with the gut microbiota in the context of arthritis." (PMID 38803575, 2024). "While previous research has shown that butyrate, a fermentation product of gut microbiota, enhances SESN2 expression in the liver, its influence on arthritis progression has not been explored." (PMID 38803575, 2024).
astrocytoma (1 paper, 2023). "As for the histological types, high expression of SESN2 was relevant to a poorer prognosis in astrocytoma and oligodendroglioma." (PMID 36980973, 2023).
cerebrovascular diseases (1 paper, 2021). "SESN2 can diminish ROS accumulation and activate autophagy, thus suppressing cancer, respiratory‐related diseases, cardiovascular diseases and cerebrovascular diseases." (PMID 33942488, 2021). "This review discusses the regulatory mechanisms of SESN2 and highlights the significance of SESN2 as a biomarker and therapeutic target in hypoxia‐related diseases, such as cancer, respiratory‐related diseases, cardiovascular diseases and cerebrovascular diseases." (PMID 33942488, 2021).
cholestasis (1 paper, 2022). Impairment of the bile flow caused by obstruction within the liver, or outside the liver in the bile duct system. "Immunoblot analysis of livers from Sesn2−/− mice showed marked exacerbation of ER stress upon cholestasis, as evidenced by elevated levels of phosphorylated elF2α and ATF4." (PMID 35260799, 2022).
chronic renal failure (1 paper, 2020). "LSD1, upon deacetylation by histone deacetylase 1 (HDAC1), reduced the methylations of H3K4me2 in the promoter region of Sesn2, thereby suppressed the gene expression of Sesn2 in chronic renal failure (CRF)." (PMID 33425907, 2020).
colon adenoma (1 paper, 2016). An adenoma that arises from the colon. "Tumors developed in both WT and Sesn2-/- mice displayed classical characteristics of colon adenomas, such as nuclear β-catenin staining, increased cell proliferation (PCNA staining), DNA damage (γ-H2AX staining) and apoptotic cell death (TUNEL staining)." (PMID 26913956, 2016).
COVID-19 (1 paper, 2024). A disease caused by infection with severe acute respiratory syndrome coronavirus 2. "We observed increased expression of Sestrin-2 in the COVID-19+ cohort compared to the control cohort." (PMID 38715114, 2024).
depression (1 paper, 2020). "It was largely unknown the potential mechanism of chronic DOX-stimulation induced depression on SESN2 transcription." (PMID 33117796, 2020).
diabetic cardiomyopathy (1 paper, 2025). Diabetic cardiomyopathy is a disorder of the heart muscle in people with diabetes. "A recent study revealed that the inhibition of SESN2 attenuates cell apoptosis and oxidative stress in an in vitro model of diabetic cardiomyopathy." (PMID 39037665, 2025).
disc degeneration (1 paper, 2023). "NR could promote the level of UPRmt in the disc degeneration of Sesn2-/- mice, but could not increase the level of mitophagy in the disc degeneration of Sesn2-/- mice." (PMID 36632468, 2023).
Duchenne muscular dystrophy (1 paper, 2024). Duchenne muscular dystrophy (DMD) is a neuromuscular disease characterized by rapidly progressive muscle weakness and wasting due to degeneration of skeletal, smooth and cardiac muscle. "This study was conducted to analyze the role of Sesn2 in the myogenic differentiation of C2C12 myoblasts and related aspects in mdx mice, an animal model of Duchenne muscular dystrophy (DMD)." (PMID 39117956, 2024).
dystrophin deficiency (1 paper, 2023). "Antithetical expression of SESN2 by diet and disease is suggestive of independent mechanisms regulating SESN2 abundance during IR and dystrophin deficiency and is also reflective of the complexity of SESN2 regulation." (PMID 37811713, 2023). "We identified a differential response of SESN2 to dystrophin deficiency and HFHSD, suggesting that SESN2 is sensitive to the cellular and metabolic effects of both DMD and DI-IR." (PMID 37811713, 2023).
endometrial adenosquamous carcinoma (1 paper, 2019). A rare endometrial carcinoma characterized by the presence of both malignant glandular and malignant squamous cellular components. "Moreover, we observed strong expression of SESN2 protein in RL-92-5 cells derived from a moderately differentiated G2 endometrial adenosquamous carcinoma representing type I." (PMID 31073887, 2019).
endometriosis (1 paper, 2026). The growth of functional endometrial tissue in anatomic sites outside the uterine body. "SESN2, in particular, emerges as a promising biomarker candidate for disease presence, warranting further validation in larger and more diverse endometriosis cohorts." (PMID 41751304, 2026).
ganglioneuroma (1 paper, 2017). A benign neuroblastic tumor of the sympathetic nervous system that occurs in childhood. "Next, we analyzed LSD1 and SESN2 expression in a microarray gene expression data of 61 NBs (GSE12460), of which 50 were NB, 9 were ganglioblastoma and ganglioneuromas, and 2 were NB post chemotherapy." (PMID 28783174, 2017).
Hashimoto’s disease (1 paper, 2025). "An increase in TSH level increased the risk of developing Hashimoto’s disease by 2.844 times (95% confidence interval: 1.834–4.41, P < 0.001), while a decrease in serum SESN2 level increased the risk of the disease by 0.789 times (95% confidence interval: 0.658–0.947, P = 0.011)." (PMID 40956676, 2025). "Longitudinal evaluation of the role of SESN2 in Hashimoto’s disease and investigation of new treatment approaches targeting this protein are considered important areas for future studies." (PMID 40956676, 2025). "The aim of this study was to investigate the potential role and importance of SESN2 in Hashimoto’s disease." (PMID 40956676, 2025). "The aim of this study was to investigate the potential role and significance of sestrin 2 (SESN2), a member of the sestrin family, in Hashimoto’s disease." (PMID 40956676, 2025). "In our study evaluating SESN2 levels in Hashimoto’s disease, we found that SESN2 levels were lower in patients with Hashimoto’s disease compared to healthy adults." (PMID 40956676, 2025). "In this study, it was found that the serum SESN2 levels of patients with Hashimoto’s disease were lower than those of healthy adults." (PMID 40956676, 2025). "Considering the relationship between Hashimoto’s disease and PTC, the low SESN2 levels in PTC cells support the low SESN2 levels in Hashimoto’s disease detected in our study." (PMID 40956676, 2025). "In the ROC curve analysis performed to determine how effective a factor serum SESN2 measurements are in distinguishing Hashimoto’s disease patients from the control group, the area under the curve was calculated as 0.644 (95% CI: 0.560–0.727)." (PMID 40956676, 2025). "In this context, the potential role of SESN2 in Hashimoto’s disease may contribute to both the understanding of the pathophysiology of the disease and the development of new treatment approaches." (PMID 40956676, 2025). "The known relationship between SESN2 and mTOR suggests that the high mTOR levels observed in Hashimoto’s disease may be due to low SESN2 levels in patients, as in PTC." (PMID 40956676, 2025). "When we interpret this finding in conjunction with previous studies in the literature, we suggest that the decrease in SESN2 levels in Hashimoto’s disease may lead to increased mTOR expression, ultimately resulting in suppressed autophagy." (PMID 40956676, 2025). "In this study on MS, SESN2 levels were found to be low, as we found in Hashimoto’s disease." (PMID 40956676, 2025). "In this study, serum SESN2 levels were found to be lower in patients with Hashimoto’s disease than in healthy adults, suggesting that SESN2 may have a role in the pathophysiology of Hashimoto’s disease." (PMID 40956676, 2025).
Hepatitis (1 paper, 2019). Inflammation of the liver. "In d-galactosamine (Gal)/LPS-induced hepatitis, TLR activation participated in SESN2 induction in liver macrophages, and SESN2 attenuated LPS-induced pro-inflammatory cytokines, hepatic cell death, and liver damage." (PMID 31867002, 2019).
hepatitis B (1 paper, 2021). "The expression of sestrin 2 in HCC was lower than that in non-cancerous tissues, and lower sestrin 2 expression was associated with hepatitis B/hepatitis C viral infections, lymph node metastasis, tumor progression, and poor prognosis in HCC patients." (PMID 34784907, 2021).
Hyperinsulinemia (1 paper, 2015). An increased concentration of insulin in the blood. "In addition, in high-fat-diet-fed mice both mTOR overactivation and elevated SESN2 expression were evident; we proposed that that hyperinsulinemia-evoked mTOR activation might upregulate SESN2 protein level." (PMID 25792980, 2015).
hypoxia (1 paper, 2021). A decrease in the amount of oxygen in the body. "Although the advantageous or disadvantageous roles of SESN2 appear in different diseases, SESN2 provides a novel therapeutic target for the prevention of hypoxia‐related diseases and metabolic disorders." (PMID 33942488, 2021).
intervertebral disc degeneration (1 paper, 2023). "Sesn2-/- mice showed a more severe degeneration and NR did not completely alleviate the intervertebral disc degeneration (IVDD) of Sesn2-/- mice." (PMID 36632468, 2023).
ischemia reperfusion injury (1 paper, 2025). Adverse functional, metabolic, or structural changes in ischemic tissues resulting from the restoration of blood flow to the tissue (reperfusion), including swelling; hemorrhage; necrosis; and damage from free radicals. "A comprehensive elucidation of the regulatory effects of S-PPE NP on SESN2 and KIM-1 expression in ischemia-reperfusion injury-AKI (IRI-AKI) could enhance therapeutic approaches for AKI." (PMID 40485171, 2025).
liver cirrhosis (1 paper, 2017). "In contrast, no statistical association was noticed between SESN2 expression and other clinical items, including the gender, age, liver cirrhosis, tumor size, distant metastasis, and TNM stage." (PMID 28118855, 2017).
mastitis (1 paper, 2025). Inflammation of breast tissue during lactation or postpartum due to an obstructed duct or infection. "While Nrf2's protective role in mastitis has gained attention, the mechanism that activates Sesn2/Nrf2 signaling remains underexplored in mastitis." (PMID 41281654, 2025). "LF-C3GNPs represent a potent nanomedicine for mastitis via Sesn2/Nrf2 activation, with clinical translational promise." (PMID 41281654, 2025). "In this study, LF-C3G-encapsulated nanoparticles (LF-C3GNPs) were engineered and thoroughly characterized to assess their therapeutic potential against LTA-induced inflammation and oxidative stress in mastitis, primarily via modulation of the Sesn2/Nrf2 signaling pathway." (PMID 41281654, 2025). "•LF-C3GNPs activate Sesn2/Nrf2 and inhibit STAT3/2 to restore redox balance in mastitis." (PMID 41281654, 2025).
metastatic melanoma (1 paper, 2021). A melanoma that has spread from its primary site to another anatomic site. "The detachment of metastatic melanoma cells from the extracellular matrix can induce the up-regulation of sestrin 2 expression because of suspension stress." (PMID 34784907, 2021).
muscular dystrophy (1 paper, 2024). Muscular dystrophy (MD) refers to a group of more than 30 genetic diseases characterized by progressive weakness and degeneration of the skeletal muscles that control movement. "This study could pave the way for developing targeted therapeutic strategies by regulating the miR-182-5p-Sesn2 axis to promote the function of SCs and improve regeneration in the context of muscular dystrophy, such as DMD." (PMID 39117956, 2024).
non-alcoholic fatty liver disease (1 paper, 2025). "In liver diseases such as non-alcoholic fatty liver disease (NAFLD), SESN2 (fly Sesn) slows disease progression by balancing glycolipid metabolism through macroautophagy (lipophagy) and delays the onset and progression of fibrogenesis." (PMID 40099194, 2025).
oral cancer (1 paper, 2025). "In the present study, Sesn2 expression data in TCGA and immunohistochemical staining data from the HPA database were analyzed, which showed that Sesn2 expression was upregulated in oral cancer specimens compared with normal control specimens." (PMID 41614860, 2025).
overnutrition (1 paper, 2022). An imbalanced nutritional status resulting from excessive intake of nutrients. "Overnutrition induces high expression of SESN2 in the liver of mice." (PMID 35954183, 2022).
papillary thyroid cancer (1 paper, 2024). "The general pharmacological effects on human papillary thyroid cancer cells that are related to the activation of Sestrin2 (SESN2), upregulated p‐AMPK (phosphorylated AMPK), and inhibits p‐mTOR (phosphorylated mTOR) and p‐p70S6Kinase (ribosomal protein S6 kinase)." (PMID 38230908, 2024).
peripheral nerve injury (1 paper, 2020). Injury to a peripheral nerve. "Moreover, SESN2 also controls the ROS‐dependent neuropathic pain signalling pathway following peripheral nerve injury." (PMID 32363721, 2020).